INS (insulin)
Diseases named in the same sentence as INS in open-access papers (continued):
Sharing a sentence is not in itself a finding about the gene and the disease.
Obesity (continued). "The concentrations of hormones and cytokines, including insulin, leptin, adiponectin, ghrelin, and pro- and anti-inflammatory factors, were recently found to vary in human milk, which is influenced by maternal metabolic conditions, such as obesity." (PMID 35277026, 2022). "In the mouse model, it was observed that hepatocyte-specific depletion of ANGPTL4 prevents diet-induced obesity, leads to a decrease in circulating triglycerides, increases insulin sensitivity and glucose tolerance and inhibits the progression of atherosclerosis." (PMID 36144281, 2022). "SCFAs such as butyrate produced by the digestive tract bacterial processing of dietary fiber reduces the development of inflammatory and metabolic disorders in humans and improved insulin sensitivity concurrent with increased energy expenditure in murine diet-induced obesity." (PMID 35320973, 2022). "Recent studies have demonstrated that intravenous, subcutaneous, or intraperitoneal injections with antimiR-34a, antagomiR-132, LNA-29, and LNA-181a antimiRs reduce blood glucose levels, decrease inflammation, improve insulin secretion and its hepatic sensitivity in a mouse model of obesity." (PMID 36614057, 2022). "To investigate the dynamics of insulin acting on adipose tissue, we developed a novel differential-equations based model that describes the coupled dynamics of glycerol concentrations and insulin action during an oral glucose tolerance test in female adolescents with obesity and IR." (PMID 35991189, 2022). "Obesity therefore involves activated, insulin-resistant, immune cells." (PMID 35406000, 2022). "Obesity is a chronic and complex disease characterized by excessive amounts of fat within adipocytes, which may result from insulin resistance, dysregulation in lipid and other metabolic balances, and inflammatory and/or hormonal processes." (PMID 36726817, 2022). "However, some studies demonstrate involvement of TCF7L2 in body weight regulation and the development of obesity and T2D due to impairment of β-cell function and then insulin secretion." (PMID 35292917, 2022). "In addition, insulin sensitivity is improved in patients with severe obesity and metabolic syndrome when FMT is combined with a daily intake of low-fermentable fiber." (PMID 36713461, 2022). "The ameliorated obesity in the mice receiving IgG infusion was accompanied by improved glucose tolerance and insulin sensitivity, whereas enhanced HFDIO following IgA infusion was associated with greater impairment of glucose intolerance and insulin sensitivity." (PMID 35587276, 2022). "In addition to improving obesity, gallic acid has also been found to improve insulin signaling and reduce inflammation and oxidative stress." (PMID 36501200, 2022). "Elevated leptin, insulin and lipid levels are features of obesity, each of which might also contribute to differences in cardiovascular development in the next generation." (PMID 36346818, 2022). "Hypoxia induces adipocyte death and consequent macrophage recruitment; these infiltrating cells, regulated primarily by HIF-1α, play a crucial role in initiating obesity-related disorders, including metabolic reprogramming, insulin resistance, and inflammation." (PMID 35450048, 2022). "This leads to the promotion of obesity and resistance to insulin." (PMID 36320802, 2022). "However, the Zucker rat, a genetic model of obesity, displays abnormally low insulin levels in the brain, despite the expected hyperinsulinemia in the plasma." (PMID 36244663, 2022). "Therefore, the aim of this study was to assess the association between serum OPG and BNP concentrations in a young healthy population and their relation to insulin sensitivity and obesity." (PMID 35215487, 2022). "In addition the insulin target tissues, transcriptome profiling and different studies have identified several β-cell specific lncRNAs that contribute to obesity-mediated β-cell dysfunction and apoptosis." (PMID 35794109, 2022).
Obesity (continued). "According to research on how obesity may promote carcinogenesis, obesity increases insulin production, which may stimulate tumor growth." (PMID 36042998, 2022). "In agreement, we were not able to demonstrate an association between circulating APN and cIMT in a prospective study with women evaluated at baseline and 1 year after obesity surgery, albeit the observed increase in APN was associated with a reduction in insulin resistance." (PMID 36009547, 2022). "The overexpression of leptin promotes weight gain and obesity, which may force the pancreatic system to secrete more insulin in the blood, a condition termed hyperinsulinemia." (PMID 36078079, 2022). "Maternal metabolites commonly associated with obesity (TG, insulin, glucose) did not appear to be overall drivers of the changes in gene expression of placental lipid metabolism pathways in early pregnancy." (PMID 36371454, 2022). "Although the mechanisms by which obesity may drive β-cell compensatory insulin hypersecretion are still nearly unknown, numerous studies have suggested the ability of the AT secretome to regulate the β-cell insulin secretory function." (PMID 35628332, 2022). "Collectively, these data illustrate renal pathways and themes associated with obesity and suggest that a majority of them do not map onto the most obvious molecular cascades of BP regulation and/or glucose and insulin metabolism." (PMID 34893803, 2022). "Further study verified that AICAR administration in vivo led to reduced adipose tissue content and improved glucose tolerance and insulin sensitivity in a diet-induced obesity (DIO) mice model, likely through elevating PGC1α expression in adipose tissue and promoting brown/beige adipogenesis." (PMID 35216415, 2022). "Furthermore, CTPG ameliorated HFD-induced obesity by inhibiting hypertrophy and hyperplasia of adipose tissue, inflammation and improving glucolipid metabolism and insulin sensitivity, changing structure and function of gut microbiota in obese C57BL/6 N mice." (PMID 36229811, 2022). "On the other hand, OGT activity in liver cells has been linked to insulin and leptin resistance through STAT3 and PTP1B dependent pathways that are known to drive receptor desensitization in the hypothalamus, specifically in response to obesity." (PMID 36111295, 2022). "Indeed, there is evidence that high-fat diet and obesity, T2D, AD, and stress can provoke an insulin resistant–like state in the CNS." (PMID 35798912, 2022). "In our cell-based model, we have shown that MAIT cell supernatants from adults with obesity (which contained higher levels of IL-17) limited insulin-mediated glucose uptake into human muscle cells when compared with supernatants from healthy control MAIT cells." (PMID 35305128, 2022). "However, currently, we cannot conclusively attribute a role of mTOR activation by insulin on reducing protein breakdown in muscle of humans with obesity." (PMID 35350688, 2022). "In addition, the transplantation of brown fat plays an active role in combating obesity and improving insulin sensitivity in mice." (PMID 35886989, 2022). "Accordingly, despite a lower prevalence of overweight and obesity in men compared to women in our study, this ‘unfavourable’ regional fat distribution and the sex-specific relationships with insulin sensitivity and beta-cell function places them at greater risk for future T2D." (PMID 35225824, 2022). "Accordingly, systemic up-regulation of human or mouse Bace1 causes endoplasmic reticulum stress and neuronal damage reflected by hypothalamic energy homeostasis circuits impairment leading to insulin resistance, hepatic deficits, and aggravation of high fat diet-induced obesity in mice." (PMID 35873003, 2022). "Furthermore, STM inhibited obesity-induced inflammation by decreasing macrophage infiltration and proinflammatory signaling and restored insulin sensitivity to the WAT and liver." (PMID 36305727, 2022).
Obesity (continued). "Notably, when these are fed an HFD (60% kcal fat) for 12 weeks, their insulin sensitivity is further increased, and they develop early obesity, to which they rapidly adapt." (PMID 36555433, 2022). "The protective effect of obesity on leukemic cells may be through increased levels of insulin and insulin-like growth factor-1 (IGF-1), which provides a chemoprotective niche and metabolic “fuel” to promote systemic inflammation." (PMID 35509847, 2022). "However, obesity and increased accumulation of adipose tissue result in a pro-inflammatory, hyperlipidemic, and insulin-resistant environment." (PMID 35350649, 2022). "IL-1 ligands, especially IL-1β, have shown with deleterious effects on pancreatic beta-cells and IL-1Ra is protective of the insulin secretory capacity, and this anti-inflammatory action is thought to predominantly originate from adipose tissue and obesity-induced inflammation in T2DM." (PMID 36014927, 2022). "Recently, scientists have reported that RMT could be used to attenuate obesity and improve insulin signaling in visceral and subcutaneous white adipose tissue." (PMID 36353509, 2022). "Finally, our results show that the combination of CSAT+® supplementation and aerobic training is the only effective strategy to prevent obesity-induced vascular insulin resistance, pointing again to a synergistic effect between them." (PMID 36139877, 2022). "Saturated FAs are well-known factors in the impairments of insulin sensitivity in obesity." (PMID 35936891, 2022). "Studies in animals with HFD-induced obesity demonstrated that flavones markedly reduce inflammation and metabolic syndrome in obese mice—they decrease triglycerides, cholesterol, and blood glucose levels; prevent liver injury, and improve insulin sensitivity." (PMID 36555392, 2022). "While there is much excitement surrounding the use of commercial CGM products in management of obesity, our preliminary results suggest that fasting insulin and HOMA-IR values may be more clinically useful than CGM data alone." (PMID 36570168, 2022). "The increase in IL-6 levels during obesity has been linked to β-cell compensatory insulin hypersecretion as it can act directly on pancreatic β-cells, enhancing glucose-stimulated insulin secretion (GSIS) without affecting insulin content." (PMID 35628332, 2022). "We observed enhancement of mood after IN insulin for women with obesity." (PMID 35397638, 2022). "Our main finding was that non-obese young males with high risk for future obesity had increased insulin-stimulated brain glucose uptake." (PMID 34728775, 2022). "On univariate analysis, islet antibody-positive individuals were more likely to live in a rural area, to be initiated on insulin therapy at diagnosis, and exhibited lower measures of obesity (WC and WHtR) and pancreatic beta-cell function (fasting and postprandial C-peptide)." (PMID 35604955, 2022). "The complement protein results reported here are in accord with some studies on PCOS but not others; however, those studies had not taken into account the underlying pathophysiology of obesity, insulin resistance and inflammation that are addressed here." (PMID 36293087, 2022). "However, animals with loss ofAMPKβ1 exhibit reduced food intake and body mass, improved insulin sensitivity, as well as protection against diet-induced obesity and hepatic steatosis." (PMID 35880569, 2022). "Both interventions, CSAT+® supplementation and aerobic training, exert synergistic effects in preventing the obesity-induced increase in kidney weight, vascular insulin resistance, and changes in some pro-inflammatory and oxidative genes in the liver and the gastrocnemius." (PMID 36139877, 2022). "Basal concentrations and responses to an oral glucose tolerance test of glucose, insulin, C-peptide, triglyceride, NEFAs, and insulin secretion at baseline and after matched ~6% weight loss by a CD or a CRHP diet in individuals with T2D and overweight or obesity." (PMID 36061897, 2022).
Obesity (continued). "Together, our results demonstrate that C29-mediated suppression of the stable and activated ERRα3SA protein enhances whole-body insulin sensitivity as well as provides anti-obesity, anti-hyperglycemia/insulinemia/triglyceridemia, and anti-hepatic steatosis effects in HFD-fed ERRα3SA mice." (PMID 35440636, 2022). "It seems that these effects of low-GI foods might be possible through decreased glucose levels and insulin responses that lead to increased satiety and decreased energy intake to prevent obesity." (PMID 36253802, 2022). "Moreover, pregnant women with pre-pregnancy overweight/obesity have decreased insulin sensitivity as compared with lean or normal-weight women, which puts them at a higher risk of GDM." (PMID 36105207, 2022). "A study of women with polycystic ovary syndrome reports increased IL-1Ra levels together with altered insulin sensitivity and increased 2-hour glucose with obesity that showed decreasing insulinogenic and glucose disposal indices associated with increasing IL-1Ra, independently of age and BMI." (PMID 36014927, 2022). "The way insulin enters the brain is mainly through a selective transport along the capillary endothelial cells of the blood-brain barrier (BBB), which appears to be influenced by risk factors such as DM, obesity, inflammation and blood triglyceride levels." (PMID 35269827, 2022). "Determining the effect mediated by insulin sensitivity could further uncover the mechanism of lipid abnormality in individuals with upper-body obesity and potentially facilitate the development of effective intervention strategies." (PMID 36387872, 2022). "Furthermore, these models should also display features of the metabolic syndrome, such as obesity and disturbances in lipid, glucose and insulin metabolism." (PMID 36555433, 2022). "According to Pedersen’s hypothesis, elevated maternal glucose levels would increase fetal insulin production, leading to increased fetal growth and obesity." (PMID 35872998, 2022). "However, a chronic nutritional surplus induces obesity, promotes insulin insensitivity, and triggers low-grade inflammation." (PMID 36003642, 2022). "Since we showed that fhFABP1 induced changes in the Th2/Th1 balance, both in vitro and in vivo, we investigated whether repeated administration of the recombinant molecule could improve metabolic homeostasis in obesity-induced insulin-resistant mice." (PMID 35720355, 2022). "Importantly, during high fat diet-induced obesity, miR-143KO significantly reduced body weight, and improved energy expenditure, insulin sensitivity, and glucose tolerance." (PMID 36361843, 2022). "Similar to IL-6, the increase in irisin levels during obesity could mediate insulin secretion adaptation in response to increased insulin demand." (PMID 35628332, 2022). "However, it has to be pointed out that the brain is an insulin-sensitive organ, and IR has been observed in the CNS of individuals with obesity and metabolic diseases like T2DM." (PMID 35873818, 2022). "Maintaining a lower activity of insulin and increased intake of calories may result in body weight growth and, consequently, the development of obesity." (PMID 36141950, 2022). "In addition, dysregulation of the immune cell response is a major contributor to chronic systemic inflammation in obesity, with deleterious consequences for insulin sensitivity and endothelial function." (PMID 35203639, 2022). "On the one hand, in obesity, the insulin-mediated activation of the PI 3-kinase pathway is impaired, whereas the activation of the extracellular signal-regulated protein kinase 1/2 and the production of endothelin-1 by insulin are normal." (PMID 35805693, 2022). "In this sense, circulating levels of NTN-1 could reflect the degree of insulin sensitivity and potentially serve as a biomarker to indicate the severity of obesity." (PMID 36297056, 2022).
Obesity (continued). "PPAR-α connects the nutritional inputs to the activation of specific cellular gene programs, that are involved in whole-body carbohydrate and lipid metabolism, increasing free fatty acid oxidation, improving insulin resistance and energy expenditure in obesity." (PMID 35214069, 2022). "Indeed, not only does it inhibit diet-induced obesity in mice by improving insulin and leptin signaling, but also slows the growth rate of breast tumors and reduces the possibility of cancer metastasis in the lungs." (PMID 35806030, 2022). "Decreased insulin suppression in adipocyte lipolysis could contribute to enhanced basal lipolysis in obesity." (PMID 35321537, 2022). "However, further studies found that the number of Th17 cell in abdominal subcutaneous AT in insulin-resistant individuals with obesity are higher than those insulin-sensitive individuals with obesity." (PMID 36428983, 2022). "This is of particular clinical relevance as abdominal/visceral obesity, where adipose surrounds the intraabdominal organs, is directly linked to numerous pathological conditions including impaired glucose and lipid metabolism, insulin resistance, and obesity related mortality." (PMID 36291259, 2022). "Besides macrophages, the inflammatory cytokines IL6 and TNF are additionally emitted from fat tissues and are known to be increased in obesity and insulin-resistant patients." (PMID 36432581, 2022). "Studies of mice with the conditional depletion of Angptl4 in adipose tissue demonstrated that, under conditions of diet-induced obesity, gene deletion reduces circulating triglycerides and improves insulin sensitivity, whereas body weight and glucose homeostasis remained unchanged." (PMID 36074318, 2022). "Hence, we aimed to assess the association of hepatic steatosis and fibrosis with different measures of hepatic and peripheral insulin sensitivity in patients with severe obesity and T2DM." (PMID 36336684, 2022). "Cinnamon and its active ingredients such as cinnamaldehyde, cinnamate, cinnamic acid, and eugenol in the forms of aqueous and alcoholic extracts have anti-obesity effect through reduction of Ghrelin, insulin resistance, lipolysis, lipogenesis, lipid absorption in the small intestine." (PMID 36523331, 2022). "In addition to its insulin-sensitizing properties, adiponectin has been reported to protect against various obesity-related pathologies, including hypertension, heart failure, atherosclerosis, steatohepatitis, airway inflammation, and breast cancer." (PMID 35453376, 2022). "In addition, the correlation of BDNF and NGF with salivary insulin, blood pressure, and obesity measures were evaluated." (PMID 35626286, 2022). "Moreover, administration of a liver-targeted TRβ-selective agonist increases GLP-1 and insulin levels and alleviates hyperglycemia in diet-induced obesity." (PMID 36302774, 2022). "GRASP55 is the Golgi‐resident protein involved in secretory pathways of multiple cargos that bypass the Golgi and its deletion in mice leads to reduced CM secretion and abnormally large LD formation which systemically results in resistance to obesity and improved insulin sensitivity." (PMID 35437952, 2022). "Obesity is accompanied by a series of metabolic alterations, and different metabolic cytokines and hormones, such as leptin, ghrelin, insulin, as well as certain central lipids may impact the HPG axis, and participate in the fine-tuning of puberty." (PMID 36465655, 2022). "In accordance with previous studies in mice and rats, we were able to show here that, on the one hand, HFD feeding leads to the development of obesity, leptin and insulin resistance, as well as hyperlipidemia, while on the other hand, treatment with TEL can prevent these scenarios." (PMID 35431918, 2022). "In response to HFD feeding, mice with human IL-37D transgene showed a resistance to obesity that may directly contribute to their improvement of insulin action." (PMID 35383145, 2022).